CD4 (CD4 molecule)
Diseases named in the same sentence as CD4 in open-access papers (continued):
Sharing a sentence is not in itself a finding about the gene and the disease.
infection (continued). "Several recent reports have indicated that non-integrated HIV DNA in resting CD4+ T-cell is capable of integration and generating productive infection upon activation." (PMID 28678879, 2017). "CTLA4 expression by CD4+ T cells was higher in patients who developed culture positive infections compared to noninfected patients (P = .04)." (PMID 28363639, 2017). "Increased antibody titres that blocked CD4 and mediate ADCC correlated with delayed infection." (PMID 28593989, 2017). "HIV-1 replication can be inhibited in primary CD4+ T cells and macrophages in culture by IFN-I treatment, indicating some of these ISGs may play a physiological role in early infection." (PMID 29354117, 2017). "Both, CD4 and CD8 T cell responses are deterministic of whether an acute infection is resolved, or whether it progresses to chronic infection." (PMID 28862649, 2017). "In the present study, we demonstrate that Tfh are a critical CD4 T cell subset, which expand in response to T. gondii challenge and are an important source of IL-21, the cytokine that regulates CD8 exhaustion during the chronic phase of infection." (PMID 29163509, 2017). "Nonetheless since the cells resist infection they remain at a low level after the third month, which is not the case with the wild type CD4+ T-cells." (PMID 29349288, 2017). "Thus, an optimal/balanced cytokine response is needed at the initial stage of the infection for parasite clearance, and IFN-γ-producing CD4+ T cells play an important role in the immunopathogenesis of African trypanosomiasis." (PMID 27242788, 2016). "In this study, both blood and tissue from untreated SIV-infected macaques were analyzed because the numbers of productively SIV-infected myeloid cells and CD4+ T cells in tissues during infection have not previously been measured." (PMID 27030272, 2016). "There was a higher frequency of CD38+ CD4+ T cells circulating following infection in P. falciparum but not P. vivax infected volunteers." (PMID 27930660, 2016). "We sought to address this issue by assessing the “functional avidity” of the CD4 T cells specific for the large and diverse set of peptide epitopes identified after infection that showed distinct partitioning between Tfh and NonTfh." (PMID 27329272, 2016). "In conclusion, neither BmA nor ES-62 can block cis-infection of CD4 enriched T-cells while BmA can bind DC-SIGN and block HIV-1 capture and transfer." (PMID 26808476, 2016). "Throughout the course of infection, CD8+ T cells were more prevalent than CD4+ T cells." (PMID 26991092, 2016). "Further, it is assumed that CD4+ T cell help will also increase the duration of the expansion because the number of CD8+ T cells at day 6.5 is not enough to clear the infection due to the observed large virus load." (PMID 27861537, 2016). "Both IFNγ expression in CD4+ and CD8+ T cells as well as Granzyme B expression in CD8+ T cells peaked on day seven post infection which was consistent with the expression of CD11a and KLRG1 on CD8+ T cells, demonstrating that these cells were antigen-experienced effector cells." (PMID 27875529, 2016). "Thus, BCG vaccination alters the ensuing polyfunctional profile upon infection with virulent M. bovis, favoring early IFN-γ/TNF-α/IL-2 production by CD4+ Tcm cells and dampening TNF-α/IFN-γ elicited by infection." (PMID 27799930, 2016). "Supernatant produced by R848-treated activated CD4+ T cells did not protect monocytes from infection, demonstrating that the results with drug-treated monocytes were not caused by carry-over of residual R848 in the cultures." (PMID 27905985, 2016). "We were able to demonstrate that both CD4+ and CD8+ influenza virus-reactive T cells accumulate in the lungs of infected pigs from day 4 p.i. onwards, produce mainly IFN-γ and/or TNF-α, and form cross-reactive memory at the site of infection." (PMID 27512056, 2016).
infection (continued). "While several other studies found that resting CD4+ T-cells were refractory to HIV infection in vitro, our data is consistent with other studies that showed direct infection of resting CD4+ T-cells, and the establishment of latency in vitro, was possible but is inefficient and highly variable." (PMID 27383184, 2016). "R848 did not significantly protect activated CD4+ T cells or MDDCs from infection but decreased the infection of MDMs 3 to sixfold." (PMID 27905985, 2016). "Furthermore, the significant increase in CD4 and CD8 lymphocytes is compatible with such a primary infection." (PMID 27551290, 2016). "We have only sampled the spleen as a representative extra-pulmonary site of infection, and do not know the role of CD4 T cell-derived IFN-γ in other tissues." (PMID 27244558, 2016). "The current model is that CD4+ T cell help must be provided at the time of antigen exposure (by either infection, immunization, or exposure to self-antigen), as an absence of CD4+ T cell help at the time of priming results in tolerance (3, –, 9)." (PMID 26865713, 2016). "IFN-γ secreted by CD4+ Th1 cells synergises with TNF-a to activate macrophageleishmanicidal activity.Thus, IFN-γ plays a critical role in the control of the infection." (PMID 27759762, 2016). "CD4+ RTE expression of activation markers downstream of TCR signalling would suggest that CD4+ RTEs are encountering APCs during infection but are not becoming efficiently primed." (PMID 27658046, 2016). "Small ruminant lentiviruses (SRLVs) use the immune system cells, e.g., macrophages, to replicate themselves, and CD4+ T cells (without infecting them) to create the infection." (PMID 27399757, 2016). "In this study, we have identified a distinctive CD4+ T cell transcriptomic signature which clearly segregates BTB infected from HC cattle, indicating clear functional divergence in this key cell subset in response to infection." (PMID 27507428, 2016). "In this approach, we cannot track Mtb-specific CD4 T cells with tetramers due to the extremely low frequency of donor cells, so we assume that the transferred CD4 T cells that have upregulated CD44 are responding to the infection." (PMID 27244558, 2016). "Lamina propria mononuclear cells (LPMCs) from 11 donors were infected with HIVBaL in the presence or absence of E. coli and, at 4 days post infection (dpi), infection levels were evaluated by intracellular flow cytometry and viable CD4 T cells counted." (PMID 26762145, 2016). "There were no significant CD4+ T-cell count differences with regard to single (HBV-A) or dual infection (HBV-A + HBV-G), both in the HIV-negative or positive groups." (PMID 27286832, 2016). "The central doctrine of mycobacterial immunity relies on CD4+ T cell IFN-γ production; however, this measurement fails to differentiate infection from disease, predict those at high risk for progression, or predict vaccine immunogenicity." (PMID 27006526, 2016). "Lung CD4+ T-cell subsets were then examined at 2 and 4 days post-secondary infection: GM-CSF+ CD4+ T cells (respectively), IL-4+ CD4+ T cells (respectively), IFN-γ+ CD4+ T cells (respectively), and IL-17+ CD4+ T cells (respectively)." (PMID 27242785, 2016). "Thus, the dominant populations of FLUAVsw-specific IFN-γ-producing CD4+ and CD8+ T cells identified in various organs in this study are likely to have contributed to controlling the infection." (PMID 27512056, 2016). "Naive CD4+ T-cell numbers declined throughout infection, with no sign of a biphasic pattern, while naive CD8+ T-cell numbers remained stable during the 5-year follow-up." (PMID 27010200, 2016). "Our system is intended to mimic the in vivo situation of a primed, but not fully differentiated, human CD4 T cell entering a site of infection, where it will encounter inflammatory signals and antigen." (PMID 27280403, 2016).
infection (continued). "For example, the passive transfer of convalescent (immune) serum to naive C57BL/6 mice depleted of CD4+ T cells fails to protect the mice against primary Chlamydia genital infection (mice are unable to resolve infection and shed very high numbers of bacteria)." (PMID 27600502, 2016). "During early infection, infected DC can transmit HIV-1 to tissue resident CD4+ T cells at the mucosa or move from the mucosa to the lymph node where they come into contact with CD4+ T cells and are able to transmit the virus to these permissive target cells." (PMID 26858771, 2016). "We demonstrate that BmA, but not ES-62, can potently bind DC-SIGN and inhibit HIV-1 trans-infection of CD4+ enriched T-cells, whilst neither antigen can block cis-infection." (PMID 26808476, 2016). "While CD4+ T cells only had a significant increase in the percentage of CD44+ activated TEM cells, CD8+ T cells demonstrated a significant increase in both, CD44+ and CD44- subsets after infection." (PMID 27272720, 2016). "CD8+ and CD4+ T immune cells were obtained from C57BL/6 wild-type mice on day 21 post R. typhi infection and first transferred into C57BL/6 RAG1-/- mice either on day 45 or on day 55 post infection." (PMID 27875529, 2016). "We observed that the absence of functional Nod2 did not alter the absolute number of peritoneal exudates cells after 5 days of infection (data not shown), as well as the proportion of macrophages (CD11b+ cells), neutrophils (Ly6G+ cells) and CD4+ cells." (PMID 27377650, 2016). "Neither CD4+ T cell deficient C57BL/6 MHCII-/- nor CD8+ T cell-deficient C57BL/6 MHCI-/- mice developed disease and survived the infection." (PMID 27875529, 2016). "The HeLa-CD4 cells were initially infected by HIV-1NL4-3, and the cells were then transfected with pGL4-let-7i and the Renilla luciferase control reporter vector pRL-TK at two days post infection." (PMID 27145859, 2016). "Early innate responses to infection were maintained in these animals, but later adaptive responses were compromised: their CD4+ and CD8+ T cells produced substantially less IFN-γ than wild-type controls at a time during infection when this cytokine is known to be important for protective responses." (PMID 27023613, 2016). "Taken together, these results strongly demonstrate the combined effect of 2 miRs (one up-regulated in the BMDC, and the other in CD4+ T-cells) in contributing to anti-Cm immune responses and IFN-γ production reported previously to be critical for protection against a genital Cm infection." (PMID 27556515, 2016). "Consistent with this is our observation that there were no changes in the cytotoxic phenotype of circulating CD38+ CD4+ T cells were observed in the volunteers following infection." (PMID 27662621, 2016). "Some SIV transmission studies showed that activated CD4 cells but not DCs are the initial targets of infection." (PMID 27906032, 2016). "This means that CD4+ T-cells, which are rapidly transcribing and translating HIV, and are soon likely to die, can transfer HIV to DCs, which frequently interact with naïve CD4+ T-cells, thereby maintaining the infection." (PMID 28936255, 2016). "We conclude that unintegrated HIV-1 should be accounted for in models employing direct infection of non-proliferating cells such as resting CD4 T cells." (PMID 26728316, 2016). "Because HIV affects the CD4+ T-cell (CD4) counts in the human body, it can be employed to make appropriate decisions for the initiation of ART and proper management of the progression of the infection." (PMID 27475982, 2016). "Although we did not observe any significant differences by infection status with regards to CD4+ T-cell subset BrdU labeling, we further investigated if differences in subset proliferation were evident." (PMID 27227993, 2016). "Enhanced infection appears to be primarily mediated indirectly through increased expression of CCR5 on LP CD4 T cells without concomitant large scale T cell activation." (PMID 26762145, 2016).
infection (continued). "One group described that infection of resting CD4+ T-cells was possible without CCL19 in all donors." (PMID 27383184, 2016). "Moreover, at high dose PR8 infection (10 LD50), CD4 effectors and passive transfer of antibodies protected B cell-deficient mice from highly pathogenic H1N1 infection." (PMID 27014272, 2016). "Most importantly, viruses detected in plasma are not largely responsible for de novo infection events detected in circulating CD4+ T cells." (PMID 27484989, 2016). "CD8+ and CD4+ cell responses to the unaltered HA protein were unchanged and infection by the attenuated viruses did not appear to alter the hierarchy of dominant epitopes in the peptides measured." (PMID 26878752, 2016). "The positive relationship that we and others observed between the intensity of specific CD4 T-cell responses and plasma viral load suggests that CD4 responses do not contribute to the control of viral replication in this early phase of infection." (PMID 27746782, 2016). "Percentages of IFNγ-producing CD4+ and CD8+ T cells were significantly higher in leptin-treated infected mice compared with untreated infected mice after 60 days of infection." (PMID 27114296, 2016). "In determining the percentages of CD4+T-cells that produced IL-2, the mice immunised with mc2-CMX and BCG hadsignificantly higher levels than the PBS group, but only the mc2-CMX hadsignificantly higher levels when compared to the infection group." (PMID 27074251, 2016). "Resting CD4+ T-cells, with or without CCL19, were not susceptible to infection using virus stocks with a TCID50 <0.5, as measured by lack of integration and low RT." (PMID 27383184, 2016). "Because the activated CD4+ T cells support productive infection of HIV-1, the triggers of cell death here are most likely direct viral cytotoxicity and/or activation-induced cell death (AICD) as shown in uninfected CD4+ T cell experiments." (PMID 27145859, 2016). "In fact, the activity of iBALT is sufficient to prime MTB-specific IFNγ-producing CD4 T cells and control infection, without contributions from conventional secondary lymphoid organs." (PMID 27446088, 2016). "However, since splenic cellularity increased after infection, the absolute number of CD4+ cells, as well as CD8+ cells and granulocytes, showed significant increases after infection." (PMID 27315117, 2016). "As CXCR3+ CD4+ T-cells are the main cellular targets of HIV, it is conceivable that IP-10 enhances the trafficking of HIV target cells to lymphoid tissues, thereby promoting new rounds of infection and helping to establish viral reservoirs." (PMID 27509048, 2016). "To determine how the antigen-specific CD4+ T cell response is affected by aging, we used a MHC Class II influenza nucleoprotein (NP)-specific tetramer to track cells in young and aged mice following infection." (PMID 27109638, 2016). "Ccr5−/− recipients of CCR5+CD4+Foxp3+ Tregs had a higher number of CD4+Foxp3+ Tregs in the CNS at 5 days after infection, compared to Ccr5−/− mice that did not receive Tregs." (PMID 27439902, 2016). "To evaluate the requirement of CD4 for infection, we incubated viruses displaying the WT and L193A Envs with CD4-negative, CCR5-expressing cells and measured the ability of different concentrations of the CD4MC DMJ-II-121 or sCD4 to activate infection." (PMID 27795397, 2016). "We demonstrate that neutralization breadth in VC was strongly associated with increased frequencies of CD8+CD57+ T cells independent of VL, CD4 count or duration of infection." (PMID 27938646, 2016). "Similarly, of 20 HCV regions frequently targeted by CD4+ cells in HCV genotype-1 infection, overlapping T cell responses in HCV genotype-3 infection were only detected in 2 cases." (PMID 26092843, 2016). "CD4+ T-cells infected with B- and C-EnvEC and Env recombinant virus pairs for 48 hours were co-cultured with TZM-bl cells in the presence of indinavir to avoid any concomitant infection by free virions." (PMID 27598717, 2016).
infection (continued). "It is unclear why resting CD4+ T-cells from some, but not all, donors are permissive to direct infection without CCL19." (PMID 27383184, 2016). "Taken together, lethal challenge did not provide virus antigens for HA-specific CD4+ T cell activation in mice with protection from prior intranasal inoculation (pre-infection)." (PMID 27596047, 2016). "Using this method, absolute CD4+ counts in non-vaccinated animals were found to be stable during acute infection, while the absolute CD8+ counts were significantly decreased." (PMID 27634113, 2016). "Our data demonstrate the requirement of Vpr for efficient and productive infection of non-activated primary CD4+ T cells." (PMID 27383627, 2016). "pDCs were also studied in this model and, despite an increase in their numbers during infection, they played no role in CD4+ T cell activation or in the control of infection." (PMID 27110574, 2016). "Of note, under our reactivation protocol, no more than 7% of the endogenously-infected primary CD4+ T cells were p24+ after 7 days of culture, suggesting that the absence of F240 recognition is not due to late stage infection." (PMID 27827447, 2016). "The Treg-driven persistence of H. pylori requires T-cell-specific expression of IL-10; in fact, IL-10−/− mice and a strain lacking IL-10 expression exclusively in the CD4+ T-cell compartment are capable of spontaneously controlling experimental infections." (PMID 27322319, 2016). "Multiple organs (BM, LN, ORG, liver, lung, spleen, GI tract and FRT) were collected from EFdA-treated and untreated BLT mice at necropsy, 6 weeks post-infection (3 weeks following EFdA treatment initiation) to quantitate the levels of HIV-RNA, HIV-DNA, and CD4+ T cells." (PMID 27438728, 2016). "The proportion of cells expressing granzyme B and/or perforin within either CD38+ or CD38- CD4+ T cell subsets did not change markedly during the course of infection." (PMID 27662621, 2016). "Similar % of CD4+ T cells were observed between infected and non-infected controls during the first 6 d post-primary infection (data not shown)." (PMID 27905502, 2016). "Whole genital tracts from naive C57BL/6 mice and from CD4-depleted and nondepleted mice were harvested at 7 and 21 days following primary infection and processed for flow cytometry analysis." (PMID 27600502, 2016). "Following infection with CCR5- or CXCR4-tropic HIV, successful reproduction of HIV-1 pathogenesis in humanized mice with substantial plasma viremia and systemic depletion of human CD4+ T cells was observed." (PMID 30993244, 2016). "Limited development of a memory response was further supported by the lack of expansion of the effector memory and central memory CD4+ T cell subsets in the spleen of S. suis-infected mice, even after a boost infection." (PMID 27905502, 2016). "Upon infection, the levels of pSTAT1 and pSTAT4 within both CD38+ and CD38- CD4+ T cells decreased, while the expression of pSTAT5 was significantly decreased in the CD38+ CD4+ T cell subset only." (PMID 27662621, 2016). "The Microminipigs with defined SLA haplotypes could be a useful animal model for further research on the interaction between CD4 allomorphs and MHC molecules in disease, infection and transplantation studies." (PMID 27717346, 2016). "First, in all infection conditions, HIV preferentially integrated in actively transcribed genes as previously reported for activated and resting CD4+ T cells and the Jurkat cell line." (PMID 27459960, 2016). "There have been reports suggesting the possible infection and transmission of infection by epithelial cells even though they do not express CD4 and have undetectable or low expression of the co-receptors CCR5and CXCR4." (PMID 27998285, 2016). "Infection of TZM-bl cells with the supernatant of the CD4+T-cell-TZM-bl co-culture yielded no signal (not shown), indicating that infection by free virus is negligible in this set-up." (PMID 27598717, 2016).